CCDC33 (coiled-coil domain containing 33)
Synonyms: CT61; FLJ32855; CC2D3; HP11097
Tractability: PROTAC: ubiquitination databases record sites on it.
Gene: Protein-coding gene on chromosome 15 (74,202,705 to 74,336,472, forward strand). Ensembl gene ENSG00000140481.
Gene Ontology:
Molecular function: protein binding
Cellular component: peroxisome
Genetic constraint (gnomAD): Loss-of-function variants: 91 observed, 92.59 expected, observed/expected ratio (o/e) 0.98, 90% interval 0.83 to 1.17. The upper end of that interval is the gene's LOEUF score, 1.17, which puts it in group 5 of 6, group 1 being the genes least tolerant of losing a copy. Missense variants: 939 observed, 959.73 expected, observed/expected ratio (o/e) 0.98, 90% interval 0.93 to 1.03. Synonymous variants: 396 observed, 383.42 expected, observed/expected ratio (o/e) 1.03, 90% interval 0.95 to 1.12.
Homologues: Orthologues: chimpanzee CCDC33 (97% identical), macaque CCDC33 (94% identical), dog CCDC33 (76% identical), pig CCDC33 (74% identical), rat Ccdc33 (69% identical), mouse Ccdc33 (64% identical), tropical clawed frog ccdc33 (37% identical), zebrafish ccdc33 (18% identical).
Diseases named in the same sentence as CCDC33 in open-access papers:
CCDC33 is named in the same sentence as 5 diseases in open-access papers, as found by Europe PMC text mining. Sharing a sentence is not in itself a finding about the gene and the disease. The quoted sentences say what the papers report.
pneumococcal meningitis (2 papers, 2019 to 2020). An acute purulent infection of the meninges and subarachnoid space caused by Streptococcus pneumoniae, most prevalent in children and adults over the age of 60. "In a genome-wide association study of human and pathogen we show that human variation explains almost half of variation in susceptibility to pneumococcal meningitis and one-third of variation in severity, identifying variants in CCDC33 associated with susceptibility." (PMID 31092817, 2019). "Host variation in Coiled-Coil Domain Containing 33 (CCDC33) and serine/threonine kinase 32C (STK32C) were associated with susceptibility to pneumococcal meningitis." (PMID 32042572, 2020).
ciliopathy (1 paper, 2025). A genetic disorder of the cellular cilia or the cilia anchoring structures, the basal bodies, or of ciliary function. "As such, CCDC78 and especially CCDC33 represent interesting new candidate loci for human motile ciliopathy." (PMID 40027778, 2025). "In light of their roles in cilia beating, it is notable that neither CCDC78 nor CCDC33 has previously been associated with motile ciliopathy." (PMID 40027778, 2025).
infectious disease (1 paper, 2019). A disorder directly resulting from the presence and activity of a microbial, viral, or parasitic agent in humans. "This intronic SNP is located in CCDC33, a gene that has no prior association with infectious disease." (PMID 31092817, 2019).
CCDC33 also shares sentences with these, for which no sentence is quoted: Huntington disease (1 paper); Obesity (1).